CD226 (CD226 molecule)
Diseases named in the same sentence as CD226 in open-access papers (continued):
Sharing a sentence is not in itself a finding about the gene and the disease.
cancer (132 papers, 2009 to 2026). A tumor composed of atypical neoplastic, often pleomorphic cells that invade other tissues. "CD226-deficient NK cells exhibit impaired tumor control due to shortened contact durations with cancer cells and reduced cytotoxicity, and antibodies blocking CD226-CD155 interactions suppress NK cell-mediated cytotoxicity." (PMID 40723878, 2025). "Specifically, the increased CD226 expression in cancer tissues was significantly associated with better clinical outcomes in GC patients." (PMID 37056782, 2023). "Additionally, increased soluble CD226, and related loss of cell-surface expression, has been observed in the sera of cancer patients, suggesting some level of protease-dependent biology." (PMID 35812451, 2022). "Furthermore, CD8+ T cells with decreased or loss of CD226 expression exhibit characteristics of dysfunction, and such cells are present in tumors and correlate with resistance to cancer immunotherapy." (PMID 35263569, 2022). "In addition, CD226 polymorphisms influence cancer risk and treatment outcomes." (PMID 40723878, 2025). "These extensive preclinical evidence underscores CD226’s potential as a promising therapeutic target for cancer immunotherapy." (PMID 40723878, 2025). "Strategies to enhance CD226 signaling can bolster NK cell antitumor activity, highlighting CD226 as a promising candidate for cancer immunotherapeutic approaches." (PMID 40723878, 2025). "Emerging evidence suggests that CD226 expression is a critical determinant of the functionality of CD8+TILs and that diminished CD226 expression is implicated in conferring resistance to cancer immunotherapy." (PMID 39349829, 2024). "Among these genes, CD226 deficiency restrains CD8 + T cell function, consequently curtailing the efficacy of cancer immunotherapy." (PMID 38589454, 2024). "This review explores our current understanding of the functions of CD2 and CD226, placing a special emphasis on their potential as novel agonist targets for cancer immunotherapy." (PMID 39349829, 2024). "CD226 is a marker of highly functional T cells and contributes to cancer immune surveillance by NK cells." (PMID 36717657, 2023). "In cancer progression, CD226 was negatively regulated by TME-driven immune suppression, while IFNG and TIGIT were highly expressed in specific TILs." (PMID 37056782, 2023). "To date, attempts to modulate these immunoregulatory pathways have been centered around TIGIT antagonism and/or CD226 agonism in the context of cancer immunotherapy utilizing antibodies, with mixed results being observed in clinical trials." (PMID 36944702, 2023). "To date, TIGIT antibody antagonists have been developed to restore immune functions and allow PVR to signal though CD226 in the context of cancer immunotherapy." (PMID 36944702, 2023). "The close relations of nectins to TIGIT, CD96 and CD226 make them an interesting target for immunotherapy of cancers." (PMID 37568798, 2023). "First, we collected the single-cell RNA-sequencing pan-cancer atlas of T cells and analyzed the expression of CD226 in CD4+T cells, CD8+T cells, and Tregs." (PMID 37056782, 2023). "It has been demonstrated that as a critical activated receptor on CD8+T cells, the expression of CD226 and the frequency of CD226+CD8+TILs are significantly and positively associated with the clinical benefit of ICB in certain human cancers." (PMID 37056782, 2023). "CD226 expression by NK and T cells has been investigated in several cancer types, such as breast cancer, melanoma, pancreatic adenocarcinoma, and myeloma." (PMID 36717657, 2023). "By virtue of the clinical progression of TIGIT antagonists and emergence of novel CD96- and PVRIG-based approaches, our overall understanding of the ‘CD226 axis’ in cancer immunotherapy is starting to take shape." (PMID 35812451, 2022). "Ongoing or discontinued (terminated) clinical trials evaluating CD226 axis-related antibody-based therapies in cancer patients." (PMID 35812451, 2022).
cancer (continued). "Platelet cloaking actively disrupts the CD226/CD96–Nectin-2/Necl-5 axis of circulating cancer cells recognition and plays a significant role in metastatic cascade." (PMID 36553083, 2022). "The importance of CD226 in shaping the overall immune response has been thoroughly described in the context of autoimmunity, cancer, and viral infections." (PMID 35812451, 2022). "The authors suggested that cancer cells with high Necl-5 expression attach to CD226-expressing platelets." (PMID 36553083, 2022). "This review provides an overview of the CD226 axis in the context of cancer, with a focus on the status of immunotherapeutic strategies (TIGIT, CD96, and PVRIG) and their underlying biology (i.e., cis/trans interactions)." (PMID 35812451, 2022). "Remarkably, CD155/PVR on cancer cells interacted with CD226 expressed in CD8+ T cells in all 4 treatment groups, suggesting that this interaction plays a key role in immune modulation." (PMID 34417435, 2021). "In The Cancer Genome Atlas database analysis, we found that BCL9 expression is positively associated with CD155 and negatively associated with CD226 expression." (PMID 34417435, 2021). "CD226 downregulation has been reported in T or NK cells of patients with cancer or human immunodeficiency virus (HIV), which most likely occurs with an upregulation of PD-1 and TIGIT and impaired functionality." (PMID 33670993, 2021). "T cell Ig and ITIM domain (TIGIT)/CD226 pathway has a critical role in regulating T cell responses and has come to the forefront in cancer as a promising immunotherapeutic target." (PMID 33413573, 2021). "This review discusses the recent discoveries regarding the roles of TIGIT and CD226 in immune cell function and their potential application in cancer immunotherapy." (PMID 33670993, 2021). "Among these, in the present study, we focus on the roles of TIGIT and CD226 in regulating T and natural killer (NK) cell function and the potential therapeutic application of these receptors in cancer immunotherapies." (PMID 33670993, 2021). "Together, these observations suggest that TIGIT and CD226 potentially regulate antitumor T-cell responses and warrant further investigation of these molecules in human cancers." (PMID 30400822, 2018). "Soluble CD226 levels in serum samples from cancer patients were significantly higher than those in healthy individuals (P < 0.001), while cancer patients exhibited lower PBMC mCD226 expression than healthy individuals (P < 0.001)." (PMID 19490613, 2009). "The signal from TCR γδ stimulation is not always sufficient, and in some cases, γδ T cells may require additional receptors, such as CD226 (DNAM-1) or NKp30, to effectively kill cancer cells." (PMID 40276509, 2025). "Furthermore, the upregulation of effector‐related transcription factors and a distinct expression profile of chemokine receptors in CD226+ T cells indicate their robust effector functions and potential to contribute to improved outcomes in other cancers." (PMID 39777847, 2025). "With capecitabine monotherapy, we observed notable reductions in proliferative CD8+ T cells, an immune inhibitory effect, and increases in both CD73+CD8+ T cells and CD226+ NK cells, which could have variable implications for anti-cancer immunity." (PMID 38538574, 2024). "The role of CD226 in CD8+ T cell function has recently been described in the context of cancer." (PMID 36717657, 2023). "Therefore, we evaluated the expression patterns of TIGIT and CD226 in T and NK cells from cancer patients." (PMID 37596248, 2023). "Moreover, we found that CD226, which has cytolytic activity against cancer cells, was enriched on NK-EVs by IL-15 + IL-21 stimulation." (PMID 34316033, 2022). "Although one can speculate as to the reason(s) for study termination, given the critical position of CD226 in CD155 and CD112 axes, it will be of great interest to understand the limitations surrounding CD226 as a target for cancer immunotherapy." (PMID 35812451, 2022).
cancer (continued). "Therefore, it is reasonable that CD112 and CD155 on cancer cells are targeted by CD226 on NK-EVs, which would contribute to antitumor immune responses." (PMID 34316033, 2022). "Overall, it appears that CD226 and PD-1/PD-L1 are correlated with multiple cancer types, suggesting that CD226 activation may compliment anti-PD-L1/PD-1 immunotherapy by activating distinct T cell subsets with synergistic effects." (PMID 34417435, 2021). "CD226 downregulation is also found in Treg cells, γδ T cells, and NK cells of cancer patients." (PMID 33670993, 2021). "TIGIT and CD226 expression in healthy and cancer patient PBMCs were assessed by flow cytometry." (PMID 30400822, 2018). "Elevated sCD226 in HIV and cancer patients suggests that CD226 shedding from cell membranes occurs in a variety of diseases and could potentially be used in therapeutic monitoring." (PMID 26910838, 2016). "Thus, CD226 appears to be an integral component of the immune response in cancer, allergic inflammatory disorders, and autoimmune diseases." (PMID 26910838, 2016). "Notably, CD226 orchestrates NK cell antitumor efficacy by sustaining cytotoxic effector functions and stabilizing immune synapses with malignant cells, making it a pivotal node in cancer immune surveillance." (PMID 40723878, 2025). "Furthermore, CD226 downregulation is observed in Treg or γδ T cells in patients with cancer." (PMID 39349829, 2024). "Moreover, the increased infiltrating CD226+CD8+T cells and the increased ratio of infiltrating CD226+CD8+T cells in CD8+T subpopulation within cancer tissues could also be valuable prognostic predictors for GC patients." (PMID 37056782, 2023). "Thus, the role and mechanism of CD226 in various cancers warrants an in-depth study in the future." (PMID 32850777, 2020). "We observed a transition from CD8+ T cells expressing CD226 and CD96 to those expressing TIGIT once these cells had infiltrated into the cancer nest, consequently disrupting the immune equilibrium between the three receptors observed in healthy lungs." (PMID 38279870, 2024). "There are many activating receptors expressed by NK cells, and some examples of relevance to cancer immunotherapy include NKp46, NKp30, DNAM-1 (CD226), 2B4 (CD244), activating KIR, NKG2D, NKG2C, and NKp44." (PMID 38223411, 2024). "TIGIT competes with inhibitory receptors KIR2DL5A and PVRIG and activating receptor CD226 (DNAM-1) to bind ligands CD155 (PVR) and CD112 (Nectin-2 or PVRL2) which are commonly expressed on cancer cells and antigen-presenting cells (APCs)." (PMID 37345049, 2023). "Another mechanism to temper immune activation could be the direct regulation of CD226 expression (i.e., by ligand-induced internalization/endocytosis or cleavage), as evidenced by its modulation in various disease settings including chronic viral infection and cancer." (PMID 35812451, 2022). "In cancer, TIGIT is overexpressed and CD226 is underexpressed, and the TIGIT/CD226 pathway has gained attention as a potential clinical target for improving antitumor immune responses." (PMID 33413573, 2021). "CD155, expressed in cancer cells, binds to TIGIT on T cells to induce direct inhibitory signals and disrupt CD226-mediated T cell activation." (PMID 34025655, 2021). "While recent advances in cancer immunotherapy showed synergistic effects of simultaneous blockade of PD-1 and TIGIT, subsequent studies demonstrated the requirement of CD226 expression for this approach." (PMID 34712231, 2021). "The NK cell receptors that we examined included two types of inhibitory receptors, KIRs and NKG2A (CD94), and three activating receptors important for cancer target recognition, including NKG2D (CD314), DNAM-1 (CD226), and NKp46 (CD335)." (PMID 34325694, 2021). "In the context of cancer cell surveillance and clearance, natural-killer group 2, member D (NKG2D), CD226 (DNAM-1) and CD96 (TACTILE) bind to ligands of cellular stress often overexpressed on malignantly transformed cells." (PMID 30908480, 2019).
cancer (continued). "The second mechanism, a platelet-derived TGFβ-mediated suppression of the CD226/CD96-CD112/CD155 axis, is a novel pathway with poorly understood anti-cancer functions." (PMID 30908480, 2019). "The broad expression of CD58, CD112 and CD155 on cancer cells provided a rationale to assess CD2::CD28 and CD226::CD28 chimeras." (PMID 29707134, 2018). "TIGIT and CD226 are paired receptors that compete for shared ligands CD155 (PVR) and CD112 (Nectin-2) expressed by cancer and antigen-presenting cells." (PMID 30400822, 2018). "In NK cells, TIGIT competes with the DNAM-1 (CD226) activating receptor for their common ligands CD112 (PVRL2) and CD155 (PVR) expressed on many cancer cells." (PMID 29023417, 2017). "Finally, antibodies directed to the immune checkpoint molecules TIGIT and CD226 (DNAM-1), inhibitory receptors CD85j and CD161, and activating receptor CD314 were added as they modulate NK cell functionality and are potential targets of cancer immunotherapies." (PMID 41451217, 2025). "NK cells not only target cancer cells via single-chain antibody recognition of tumor surface antigens but also detect various ligands through multiple receptors, including NCRs, NKG2D, co-stimulatory receptor DNAM-1 (CD226), and some activating KIRs." (PMID 40299429, 2025). "Accordingly, CD226 agonism in combination with appropriate antagonistic anti-TIGIT and/or anti-CD96 antibodies represents an attractive therapeutic strategy in the context of cancer immunotherapy." (PMID 36944702, 2023). "CD226, TIGIT, and CD96 share the same ligand CD155 (also known as PVR/NECL5/TAGE4), a member of the nectin-like family of adhesion molecules and highly expressed on cancer cells." (PMID 37056782, 2023). "TIGIT, CD226 and CD96 are now broadly explored for possible targets of immunotherapy for cancer." (PMID 37568798, 2023). "While receptor heterogeneity holds true for PVR, the interplay between the receptors i.e. TIGIT blocking CD226 mediated co-stimulation, allows us to envision developing PVR as a dual functioning therapeutic with potential utilization in both cancer and autoimmune therapy." (PMID 36944702, 2023). "Despite the longstanding awareness of CD155 and CD112 expression in cancer, an understanding of their contribution to the regulation of immune function and migration was lacking until a connection with the CD226 was established." (PMID 35812451, 2022). "In an effort to provide a framework for our evolving understanding of the CD226 axis in cancer, we discuss available non-clinical data and give an overview of the current clinical landscape." (PMID 35812451, 2022). "Further studies with larger cohort should be conducted on patients from different backgrounds and disease states (different MSAs subtypes, with and without cancer) to better elucidate the role of TIGIT+CD226+ CD4 T cell in DM." (PMID 33413573, 2021). "NK cell immunoglobulin receptors CD226 and CD96 that interact with the nectin-like ligand CD112 and the polio-virus receptor CD155 on target cells are emerging as important mediators of NK cell anti-cancer functions." (PMID 30908480, 2019). "Cancer cells including TNBC cells frequently upregulate “stress” induced ligands recognized by the NK cell activating receptors NKG2D (natural-killer group 2, member D) and DNAM-1(CD226)." (PMID 29980239, 2018). "Based on these studies, we postulate that one of the factors limiting the success of TIGIT antagonism in the treatment of cancer could be due to the lack of synergistic CD226 co-stimulation." (PMID 36944702, 2023). "For example, the dysregulation of the IR TIGIT and CD226 (a stimulatory receptor that shares CD112 and CD155 ligands with TIGIT) expression in T cells was recently suspected to be involved in severe forms of autoimmune diseases, as well as in cancer and chronic viral infections." (PMID 35821240, 2022). "Together, these data indicate that CD226 expression, but not CD28 expression, is a correlate of anti-PD-L1 response in cancer." (PMID 35263569, 2022).
cancer (continued). "The linkage between CD226 expression and NF-κB in EBV-infected cells suggested that nonviral cancers with high NF-κB may also display elevated CD226 levels." (PMID 29202043, 2017).
infection (29 papers, 2010 to 2025). The state of being infected such as from the introduction of a foreign agent such as serum, vaccine, antigenic substance or organism. "We identified ten NK subgroup-specific marker molecules (Kcnj8, Cmah, Ccnd2, Cx3cr1, Thy1, Tnfrsf9, Zbtb20, Gng11, CD226, Egr3) from C0 to C9 and assessed their expression changes during infection using RT-qPCR." (PMID 40244063, 2025). "CD226 expression on immune cells is dynamically regulated during infections and correlates with immune responses." (PMID 40723878, 2025). "The relative expression level of TIGIT downregulated in the PBMCs and spleens of infected mice on the first day after infection, while the expression of costimulatory receptor CD226 in the spleen of infected mice increased significantly." (PMID 33629951, 2021). "At the same time, compared with the control group, CD226 expression on splenic T cells was significantly downregulated only in the 1st week after infection, which was negatively correlated with the expression of TIGIT." (PMID 34421855, 2021). "Then, roughly 3 weeks after infection, CD226 levels rapidly rise to the constitutively high levels of expression generally observed in LCLs." (PMID 29202043, 2017). "The most dramatic increase in CD226 surface expression occurred approximately 3 weeks after infection, which is the same time frame that EBV induces NF-κB targets concomitant with LMP1 expression." (PMID 29202043, 2017). "Infection was associated with the upregulation of proinflammatory genes CXCL10, IFNG, and IL15, alongside several NK and T cell activation markers such as CD244, CD40LG, and CD226." (PMID 39774119, 2025). "Reduced CD96−CD226+ cells and elevated CD96+CD226− cells among NK cells especially TIGIT−NK cells, had opposite associations with viral load in the first month of infection, as well as CD4 T-cell counts in including the twelfth month and more than 2 years of chronic infection." (PMID 33717085, 2021). "In addition, except that there was no prominent change in the proportion of CD226+CD4+ T cells at the 12th week after infection, CD226 expression on splenic T cells was notably higher than that of the control group since the 3rd week after infection." (PMID 34421855, 2021). "However, on the third day after infection, the number of CD226+ T cells was lower in the infection group than that in the Nc group." (PMID 33629951, 2021). "Additionally, CD226 mRNA expression in spleen increased significantly in the 1st week post infection (p < 0.01) and decreased significantly at other time points (p < 0.01)." (PMID 34421855, 2021). "Furthermore, in addition of cell adhesion functions, Nectin-2 mediates both entry and spreading of infection from various viruses and has also been reported that DNAM-1 (CD226) and TIGIT interact Nectin-2 to activate immune cells." (PMID 29723247, 2018). "The CD4+ cells also showed a mixed pattern, with higher CD226 (activation) and Tim-3 (inhibitory) expression and lower GITR (activation), CD223 and B7H5 (inhibitory) expression after secondary infection." (PMID 35743356, 2022). "It has been shown that infection with HIV-1 significantly increases the expression of KIRs on both T and NK cells, and the activating receptors NKG2C and CD226/PTA1 on peripheral blood NK cells are abnormally expressed in PLWH." (PMID 35371060, 2022). "From the 3rd day after infection, the expression of TIGIT in PBMCs and spleens of the infected group was significantly higher than in the control group, and the down-regulation of CD226 was also observed at the same time point." (PMID 33629951, 2021). "Further, at different stages of infection, CD96−CD226+ cells diminished among total NK cells, TIGIT+NK and TIGIT−NK cells, while CD96+CD226− cells expanded." (PMID 33717085, 2021).